F11R (F11 receptor)
Description:
Seems to play a role in epithelial tight junction formation. Appears early in primordial forms of cell junctions and recruits PARD3. The association of the PARD6-PARD3 complex may prevent the interaction of PARD3 with JAM1, thereby preventing tight junction assembly (By similarity). Plays a role in regulating monocyte transmigration involved in integrity of epithelial barrier (By similarity). Ligand for integrin alpha-L/beta-2 involved in memory T-cell and neutrophil transmigration. Involved in platelet activation. (Microbial infection) Acts as a receptor for Mammalian reovirus sigma-1. (Microbial infection) Acts as a receptor for Human Rotavirus strain Wa.
Synonyms: JAM-A; JAM-1; PAM-1; CD321; JAM1; JCAM; JAMA; JAM; KAT
Tractability: Antibody: UniProt places it where antibodies can reach, with high confidence; its Gene Ontology location is reachable by antibodies, with high confidence; UniProt predicts a signal peptide or a membrane-spanning region. PROTAC: ubiquitination databases record sites on it; its protein half-life has been measured.
Gene: Protein-coding gene on chromosome 1 (160,995,211 to 161,023,123, reverse strand). Ensembl gene ENSG00000158769.
Subcellular location: Cell junction, tight junction; Cell membrane
Subcellular location (Human Protein Atlas): Microtubules; Cell Junctions
Pathways (Reactome):
Cell-Cell communication: Tight junction interactions
Extracellular matrix organization: Integrin cell surface interactions
Hemostasis: Cell surface interactions at the vascular wall
Signal Transduction: TGF-beta receptor signaling in EMT (epithelial to mesenchymal transition)
Gene Ontology:
Molecular function: cadherin binding; integrin binding; PDZ domain binding; protein binding; protein homodimerization activity
Biological process: actomyosin structure organization; cell-cell adhesion; cellular response to mechanical stimulus; establishment of endothelial intestinal barrier; intestinal absorption; leukocyte cell-cell adhesion; memory T cell extravasation; negative regulation of stress fiber assembly; positive regulation of establishment of endothelial barrier; positive regulation of platelet aggregation; positive regulation of Rho protein signal transduction; protein localization to bicellular tight junction; protein localization to plasma membrane; regulation of actin cytoskeleton organization; regulation of bicellular tight junction assembly; regulation of cell shape; regulation of cytoskeleton organization; regulation of membrane permeability; inflammatory response; maintenance of blood-brain barrier; cell adhesion; cell differentiation; leukocyte migration; regulation of cytokine production; system process
Cellular component: bicellular tight junction; cell junction; extracellular exosome; plasma membrane; protein-containing complex; tight junction; cell-cell junction
Genetic constraint (gnomAD): Loss-of-function variants: 27 observed, 41.38 expected, observed/expected ratio (o/e) 0.65, 90% interval 0.48 to 0.9. The upper end of that interval is the gene's LOEUF score, 0.9, which puts it in group 3 of 6, group 1 being the genes least tolerant of losing a copy. Missense variants: 335 observed, 393.56 expected, observed/expected ratio (o/e) 0.85, 90% interval 0.78 to 0.93. Synonymous variants: 131 observed, 153.94 expected, observed/expected ratio (o/e) 0.85, 90% interval 0.74 to 0.98.
Homologues: Orthologues: macaque F11R (97% identical), chimpanzee F11R (96% identical), rabbit F11R (80% identical), dog F11R (77% identical), pig F11R (74% identical), guinea pig F11R (73% identical), rat F11r (70% identical), mouse F11r (69% identical), rat AABR07006111.1 (62% identical), zebrafish f11r.1 (42% identical), tropical clawed frog f11r (40% identical), zebrafish f11r.2 (32% identical). Paralogues in human: JAM3 (32% identical), JAM2 (31% identical), CXADR (22% identical), IGSF11 (21% identical), VSIG1 (21% identical), ESAM (20% identical), VSIG2 (20% identical), GPA33 (19% identical), VSIG8 (19% identical), MXRA8 (18% identical), CLMP (18% identical), MUC15 (13% identical), and 2 more.
Diseases named in the same sentence as F11R in open-access papers:
F11R is named in the same sentence as 165 diseases in open-access papers, as found by Europe PMC text mining. Sharing a sentence is not in itself a finding about the gene and the disease. The quoted sentences say what the papers report.
breast carcinoma (49 papers, 2011 to 2025). "The aberrant expression of a tight junction (TJ) protein known as F11 platelet receptor aka junctional adhesion molecule-A (F11R/JAM-A) is linked with most cancer types, particularly with breast cancer." (PMID 37563645, 2023). "In a summary, the overexpression of F11R gene is characteristic for breast cancer–that is particularly prevalent in TNBC–and linked with poor prognosis, that is related with the decreased survival rate." (PMID 37563645, 2023). "Increasing breast cancer cell susceptibility to apoptosis and reduction of aggressive tumor behavior are associated with F11R/JAM-A loss." (PMID 34533648, 2022). "Another mechanism of action is associated with the fact that F11R/JAM-A acts as a survival factor for mammary carcinoma cells by protecting tumor cells from apoptosis." (PMID 34533648, 2022). "Moreover, F11R/JAM-A was implicated in inhibition of TNBC breast cancer cell line MDA-MB-231 invasion by an antibody targeting the tetraspanin CD81." (PMID 37563645, 2023). "Additionally, expression of the epithelial tight junction assembly factor gene F11R has been linked to breast cancer progression and patient survival." (PMID 30181541, 2018). "We confirmed A-to-I(G) editing in the 3’UTRs of MDM2 (Mouse Double Minute 2 homolog), GINS1 (GINS Complex Subunit 1), and F11R (Junctional Adhesion Molecule A) in breast cancer cells." (PMID 40381037, 2025). "The initial editing predictions for MDM2, GINS1, and F11R, obtained from the TCGA breast cancer patient dataset was experimentally validated." (PMID 40381037, 2025). "F11R/JAM-A is a direct target of transcriptional regulation by miR-145 microRNA whose overexpression in breast cancer cells reduced the F11R/JAM-A level and decreased the cell migration." (PMID 37563645, 2023). "Tetrocarcin-A was also shown to disturb the growth of HER2-positive breast cancer cells by the decrease of F11R/JAM-A protein level." (PMID 37563645, 2023). "The increased level of F11R/JAM-A transcription is notified in breast cancer and is especially apparent in TNBC, being a hallmark of poor prognosis due to decreased survival rate." (PMID 37563645, 2023). "We have previously demonstrated, that the F11R/JAM-A antagonistic peptide 4D blocks the interactions between breast cancer cells and endothelial monolayer, including adhesion and TEM in vitro." (PMID 37563645, 2023). "Their studies demonstrated that poor prognosis in breast cancer patients correlates with F11R/JAM-A overexpression." (PMID 34533648, 2022). "Reduced F11R/JAM-A expression and breast cancer cell motility as well as invasiveness are modulated by the enhanced miR-145 expression." (PMID 34533648, 2022). "In fact, F11R has been widely described in cancer development and progression, and the expression of F11R correlates with poor breast cancer prognosis." (PMID 35033985, 2022). "Conversely, miR-495 upregulation in breast cancer tissue specimens and F11R/JAM-A as its potential target were proved." (PMID 34533648, 2022). "In semi in vivo and in vitro breast cancer models, invasive potential of cancer cells was intensified by cleaved F11R/JAM-A." (PMID 34533648, 2022). "Initially, the invasion of breast cancer cells was shown to be induced by the F11R/JAM-A downregulation." (PMID 34533648, 2022). "F11R/JAM-A protein can be considered as a novel target in the treatment of breast cancer metastasis." (PMID 31650345, 2020). "To examine the involvement of the F11R/JAM-A protein in breast cancer metastasis, we utilized the F11R/JAM-A antagonistic peptide 4D (P4D) in experiments of transendothelial migration (TEM) of breast cancer cells." (PMID 31650345, 2020). "The aberrant expression of F11R/JAM-A contributes to tumor progression and its role is best studied in breast cancer." (PMID 31650345, 2020).
breast carcinoma (continued). "In order to define the role of F11R/JAM-A in breast cancer metastasis, we utilized a peptide derived from the sequence of the F11R/JAM-A protein, peptide 4D (P4D), which blocks the homophilic interactions between the F11R/JAM-A molecules." (PMID 31650345, 2020). "Moreover, the reduction of growth of patient-derived primary breast cancer cells and lung cancer stem cells alongside the F11R/JAM-A protein downregulation was due to cell treatment by Tetrocarcin-A." (PMID 37563645, 2023). "The homophilic F11R/JAM-A interactions are also necessary for TEM of breast cancer cells." (PMID 37563645, 2023). "Moreover, in our in vivo experiments the F11R/JAM-A antagonist peptide 4D evidently inhibits the metastasis in the 4T1 breast cancer mouse model." (PMID 37563645, 2023). "Similar signaling pathways are involved in breast cancer progression through F11R/JAM-A." (PMID 34533648, 2022). "The F11R/JAM-A role in breast cancer progression and metastasis remains a controversial issue." (PMID 34533648, 2022). "Interestingly, subsequent investigations revealed that aggressive breast cancer phenotypes are characterized by F11R/JAM-A and human epidermal growth factor receptor-2 (HER2) overexpression." (PMID 34533648, 2022). "However, the significance of F11R/JAM-A in breast cancer is controversial, since loss of F11R/JAM-A induces the breast cancer cell invasion, whereas the overexpression of this protein correlates with poor prognosis." (PMID 31650345, 2020). "The lowered F11R/JAM-A expression in MDA-MB-231 cells as compared with two other MEC lines is in accordance with the previously reported negative correlation of JAM-A expression with the metastatic potential of breast cancer cells." (PMID 31650345, 2020). "We demonstrate the role of F11R/JAM-A in breast cancer metastasis." (PMID 31650345, 2020). "Consequently, we employed the F11R/JAM-A antagonistic peptide 4D that blocked the breast cancer cell adhesion to the inflamed endothelium, which was particularly evident for MDA-MB-231 cells." (PMID 31650345, 2020). "Therefore, we have performed tests in vitro on cell lines and in vivo on 4T1 breast cancer murine model, whether the F11R/JAM-A peptide antagonist P4D can be efficient when used for the targeted molecular therapy in TNBC." (PMID 37563645, 2023). "Using TCGA RNA-seq data, we identified differentially edited 3’UTRs in breast cancers and experimentally validated editing sites in the 3’UTRs of MDM2, GINS1, and F11R regulated by ADAR1 with protein level implications." (PMID 40381037, 2025). "For instance, one study showed that F11R can induce EMT and serve as a prognostic factor for breast cancer." (PMID 38375422, 2024). "By exploring genes commonly identified in the both analyses, F11R and PTGIR were characterized as membrane markers in CTCs of mesenchymal state in breast cancer, which were evaluated by enriched terms, literature evidence, and relevant molecular pathways." (PMID 38375422, 2024). "As a result, we characterized F11R and PTGIR as novel membrane markers in CTCs of mesenchymal state in breast cancer." (PMID 38375422, 2024). "As a result, we proposed F11R and PTGIR as new membrane markers for detecting CTCs of mesenchymal state in breast cancer." (PMID 38375422, 2024). "The F11R/JAM-A antagonistic peptide P4D has altered the morphology of the endothelial (EA.hy926, HMEC-1) and breast cancer (MDA-MB-231) cell lines grown for 7 days in monolayers." (PMID 37563645, 2023). "The F11R/JAM-A cell adhesion protein was examined as the therapeutic target in triple negative breast cancer (TNBC) with the use of the peptide antagonist to F11R/JAM-A, that previously inhibited the early stages of breast cancer metastasis in vitro." (PMID 37563645, 2023). "Hitherto, the effects of aberrant F11R/JAM-A expression and its potential mechanisms in breast cancer have been best studied." (PMID 34533648, 2022).
breast carcinoma (continued). "Wang and Liu revealed the link between the F11R/JAM-A expression and transforming growth factor-β1 (TGF-β1) signaling in the regulation of breast cancer cell proliferation and invasion." (PMID 34533648, 2022). "In the murine 4T1 breast cancer model, administration of Tβ4 and TGF-β1 decreased the sJAM-A levels in murine blood, and a peptide derived from the sequence of the F11R/JAM-A protein, peptide 4D (P4D), blocked the TEM of breast cancer cells in the presence of TNF/IFN and Tβ4." (PMID 35356274, 2022). "Interestingly, in breast cancer, TGF-β signaling is also involved in cancer progression through F11R/JAM-A participation." (PMID 34533648, 2022). "F11R/JAM-A was shown to promote TEM of monocytes in breast cancer and to inhibit TEM of melanoma cells, but its direct effect on TEM of breast cancer cells has never been studied." (PMID 31650345, 2020).
atherosclerosis (21 papers, 2011 to 2025). A disease characterized by the build-up of fatty material and calcium deposition in the arterial wall resulting in partial or complete occlusion of the arterial lumen. "In mouse models of atherosclerosis, increased f11r messenger ribonucleic acid (mRNA) expression was found in both early atherosclerotic endothelium of carotid arteries and advanced atherosclerotic plaques." (PMID 33324419, 2020). "•The new data reported here represent the first step in the development of a novel class of drugs, based on the sequence of F11R/JAM-A, to be used for the prevention and treatment of atherosclerosis." (PMID 32395574, 2020). "We conclude that the transcription and translation of the human F11R gene are required initial steps of atherogenesis induced by inflammatory cytokines in the vasculature, leading to atherosclerosis, heart attacks and stroke." (PMID 21703019, 2011). "A role for F11r in promoting atherosclerosis has previously been reported." (PMID 35799890, 2022). "Because platelet adhesion to an inflamed endothelium is crucial for plaque formation in non-denuded blood vessels, we conclude that the de-novo translation of F11R is a crucial early step in the initiation of atherogenesis, leading to atherosclerosis, heart attacks and stroke." (PMID 21703019, 2011). "Accordingly, we propose that specific antagonists of the pathological actions of F11R represent a new target for the development of novel drugs for the prevention and treatment of atherosclerosis, heart attacks, stroke, and other cardiovascular disorders triggered by inflammatory processes." (PMID 21703019, 2011). "There are already reports that F11R antagonists are therapeutic agents for the prevention and treatment of thrombosis, atherosclerosis, heart attacks, strokes, and other clinical disorders, but whether F11R antagonists can be used in treating malignant tumors is still prelimited." (PMID 35295710, 2022). "The soluble human F11 receptor (sF11R) and annexin A5 (ANXA5) play crucial roles in inflammatory thrombosis and atherosclerosis." (PMID 36009365, 2022). "Additionally, CD40, F11R, TNRC18, and calcium/calmodulin-dependent protein kinase type II gamma (CAMK2G) were screened out and validated using enzyme-linked immunosorbent assay (ELISA) in an independent patient cohort and immunohistochemical (IHC) staining in an atherosclerosis mouse model." (PMID 32714363, 2020). "Interestingly, we observed that the immunoinflammatory biological processes and atherosclerosis deterioration-related pathways shared some common genes, including LYN, PTGIR, F11R, and C3AR1." (PMID 34095251, 2021).
nasopharyngeal carcinoma (17 papers, 2015 to 2025). A carcinoma arising from the nasopharyngeal epithelium. "F11R can also act as a tumor suppressor gene in anaplastic thyroid carcinoma and nasopharyngeal carcinoma." (PMID 35402226, 2022). "In human nasopharyngeal carcinoma (NPC), the F11R/JAM-A overexpression acts as an epithelial–mesenchymal transition inducer by the PI3K/Akt pathway activation." (PMID 34533648, 2022).
glioblastoma (12 papers, 2012 to 2024). The most malignant astrocytic tumor (WHO grade IV). "As for its distinctive function for different PDX tumor tissues, recent studies confirmed that in the PDX models of glioblastoma (soft-tissue-derived tumorigenesis), F11R has a unique expression pattern compared with other tumor tissues." (PMID 31456818, 2019). "It is interesting to note that among the down-regulated genes following SOX2 knockdown, F11R has been shown to be overexpressed in glioblastoma cells." (PMID 27669421, 2016). "Similarly, the identification of F11R/JAM-A as an essential CSC adhesion protein in patient-derived glioblastoma cells further suggests a carcinogenic role for F11R/JAM-A in driving self-renewal and tumor growth." (PMID 37563645, 2023). "In previous research, it was proved that F11R/JAM-A is a prognostic factor in glioblastomas." (PMID 34533648, 2022). "Further, F11R/JAM-A could be involved in cancer aggressiveness, in low-grade gliomas versus glioblastomas, and its level was significantly lower." (PMID 34533648, 2022). "In glioblastomas (GBM), F11R/JAM-A overexpression correlates with shorter patient survival and overall poor outcome." (PMID 34533648, 2022). "F11R/JAM-A was identified on stem cell-like brain tumor-initiating cells, which means that it probably acts as a niche adhesion factor in glioblastoma and affects brain tumor-initiating cells’ oncogenic potential." (PMID 34533648, 2022). "F11R/JAM-A may be a monocyte prognostic marker of glioblastoma (GBM)." (PMID 34533648, 2022). "Since CD81 resides inside the cell membrane of unstimulated microglia, and CLEC12A is expressed at relatively low levels in monocytes, we chose F11R and SELL as representative differentially-expressed flow cytometry markers to study monocyte infiltration in murine glioblastoma." (PMID 24147027, 2013).
multiple myeloma (12 papers, 2015 to 2024). "A series of studies revealed that the expression of F11R is inversely correlated with prognosis in many tumors, such as multiple myeloma, oral squamous cell carcinoma, and epithelial ovarian cancer." (PMID 35402226, 2022).